INS (insulin)
Diseases named in the same sentence as INS in open-access papers (continued):
Sharing a sentence is not in itself a finding about the gene and the disease.
polycystic ovary syndrome (continued). "Besides its inhibition of mTOR, metformin decreases basal and insulin-stimulated aromatase expression, which is an important mechanism of its usefulness in polycystic ovary syndrome." (PMID 29137418, 2017). "Furthermore, Sharma and Singh reported that PPARγ is involved in FSH and PI3K signaling pathways for developing polycystic ovarian syndrome in response to rosiglitazone, an insulin sensitizer." (PMID 27983712, 2016). "In addition, just OS is an important inducer of IR by post-insulin signaling defects and has interassociation with hyperandrogenemia." (PMID 26770659, 2016). "Therefore, administration of insulin sensitizers ameliorates hyperandrogenemia and ovulatory functions." (PMID 27882049, 2016). "Moreover, Wild and Bartholomew revealed that in women with PCOS altered glucose-insulin homeostasis is a stronger contributor to dyslipidaemia than hyperandrogenemia or chronic high estrogen exposure." (PMID 27239195, 2016). "High intensity interval training for ten weeks improved insulin resistance, without weight loss, in women with polycystic ovary syndrome." (PMID 26406234, 2015). "Previous studies which have cultured GC over 48 h in vitro have demonstrated that insulin-induced glucose uptake by GCs in response to increasing doses of insulin is much lower in GCs from anovulatory patients with PCOs than from women with either normal ovaries or ovulatory polycystic ovaries." (PMID 25866577, 2015). "Polycystic ovarian syndrome was commonly treated by CC and gonadotropins, but this mechanism has given a new direction towards its management with insulin sensitizing drugs that give promising results and higher success rates of ovulation as well as pregnancy, as compared with CC." (PMID 23904883, 2013). "Androgens induce polycystic ovaries in primates, and raised insulin levels secondary to insulin resistance increases the ability of the granulosa cells to respond to LH which may cause follicular arrest." (PMID 24023708, 2013). "Accumulating evidence suggests that vitamin D has a role on insulin sensitivity so may contribute to reduction of hyperandrogenemia." (PMID 25246913, 2012). "Additionally, treatment with metformin (a drug that is widely used for treating infertility in women with polycystic ovary syndrome (PCOS)) causes an activation of ERK1/2 that results in suppression of insulin-stimulated P450 aromatase mRNA expression and activity." (PMID 21637381, 2011). "Furthermore, impaired insulin signaling through AKT and AS160 changes associated with hyperandrogenemia has been documented in skeletal muscle cells from women with PCOS." (PMID 21209881, 2010). "The significance of polycystic ovarian morphology and its relation to polycystic ovary syndrome (PCOS) is unclear, but probably it is associated with higher androgen and insulin levels and lower sex hormone binding globulin (SHBG) in absence of identifiable differences in gonadotropin dynamics." (PMID 19480717, 2009). "In females, IF shows promise for improving hyperandrogenism and menstrual regularity in polycystic ovary syndrome (PCOS), mediated by enhanced insulin sensitivity and reduced free androgen index." (PMID 42280458, 2026). "Furthermore, postprandial glucose and insulin concentrations (following 75 g of glucose ingestion) have been shown to be lower following 30 hot tub sessions (of 60 min at 40.5°C) over 8–10 weeks in obese women with polycystic ovary syndrome." (PMID 39373667, 2025). "Bariatric surgery improves metabolic health and helps restore fertility by enhancing ovulatory function and insulin sensitivity, especially in women with obesity-related anovulation or polycystic ovary syndrome (PCOS)." (PMID 41523519, 2025). "The reproductive system is also directly affected by insulin, particularly in the case of polycystic ovary syndrome (PCOS)." (PMID 40725728, 2025).
polycystic ovary syndrome (continued). "Metformin enhances insulin sensitivity, diminishes oxidative stress, and safeguards ovarian function in patients with polycystic ovary syndrome (PCOS) and ovarian cancer." (PMID 40136686, 2025). "For example, metformin can reduce androgen levels and improve insulin sensitivity in polycystic ovary syndrome (PCOS), a condition often comorbid with IIH." (PMID 39816946, 2025). "In this context, supplementation with MI is successfully used in PCOS (polycystic ovary syndrome) to improve insulin sensitivity and ovulation." (PMID 41032702, 2025). "In the case of overtreatment, the mechanism of impaired insulin action is similar to that observed in Cushing syndrome, while in the second, the mechanism resembles that in polycystic ovary syndrome (PCOS)." (PMID 39240753, 2025). "It was reported that myricetin treatment improved metabolic capacity as well as insulin sensitivity by activating BAT in dehydroepiandrosterone (DHEA)-induced polycystic ovary syndrome (PCOS) mice." (PMID 40362425, 2025). "Imbalances in insulin levels, as observed in conditions like polycystic ovary syndrome (PCOS), can disrupt hormonal pathways." (PMID 38613041, 2024). "Initial studies were conducted on patients with polycystic ovary syndrome (PCOS), a dysmetabolic condition characterized by insulin resistance at the level of target tissues (adipose tissue, muscles, and liver)." (PMID 39336874, 2024). "Renin plays a significant role in the metabolic abnormalities observed in polycystic ovary syndrome (PCOS), particularly in relation to IR, as women with PCOS exhibit higher renin levels that positively correlate with insulin concentrations and HOMA-IR." (PMID 39858399, 2024). "In women with polycystic ovary syndrome, myo-inositol has been documented to improve systemic metabolic parameters such as lowering plasma triglyceride and low-density lipoprotein concentrations, while increasing high-density lipoprotein, improving insulin sensitivity, and decreasing hemoglobin A1C." (PMID 38283993, 2023). "Another study aimed to detect the effect of quercetin on adiponectin-mediated insulin sensitivity in Polycystic ovary syndrome (PCOS) patients." (PMID 38004496, 2023). "This meta-analysis was conducted to summarize the effects of n-3 polyunsaturated fatty acid (n-3 PUFA) on metabolic status including insulin metabolism and lipid metabolism in women with polycystic ovary syndrome (PCOS) by randomized controlled trials (RCTs)." (PMID 36932420, 2023). "Genistein (20 mg/kg) administration for 42 days on polycystic ovary syndrome (PCOS) rats significantly increased insulin level." (PMID 37275572, 2023). "For more than 20 years, myo-Ins have been considered a safe and effective therapy, especially for the management of Polycystic Ovary Syndrome (PCOS), an endocrine-metabolic disorder characterized by altered insulin signaling." (PMID 37513560, 2023). "IR is characterized by glucose dysregulation with elevated serum insulin level, which increases the risk for metabolic syndromes such as T2DM, CVD and polycystic ovary syndrome (PCOS)." (PMID 35281054, 2022). "Furthermore, Metformin might be an opportunity which is used for the metabolic consequences seen in polycystic ovary syndrome for its androgen-lowering and insulin-sensitizing properties." (PMID 35743898, 2022). "Insulin increases the expression of StAR but also of 17-α-hydroxylase/17,20-lyase, 3-β-hydroxysteroid dehydrogenase and aromatase, leading to the excessive production of progesterone, 17-α hydroxyprogesterone and testosterone in polycystic ovaries compared with healthy ovaries." (PMID 36009364, 2022). "Myo-Inositol and D-chiro-inositol (MI-DCI) are used in the treatment of polycystic Ovary syndrome (PCOS) due to their insulin-sensitizing actions." (PMID 36420435, 2022).
polycystic ovary syndrome (continued). "As a positive effector on insulin-resistant tissues including polycystic ovary syndrome-endometrium, myo-inositol may be a possible insulin sensitizer, triggering the activation of AMPK and increasing GLUT4 levels, which consequently increase the glucose absorption in the endometrial cells of human." (PMID 35356248, 2022). "Although studies evaluating TRX in individuals with T2D are lacking, recent research showed that this training modality improved fasting blood sugar (FBS) and insulin concentrations in women with polycystic ovary syndrome (PCOS)." (PMID 34836211, 2021). "Indeed, hyperandrogenemia is often accountable for impaired insulin sensitivity and it influences the distribution of adipose tissue with the development of insulin-signaling abnormalities and IR, abnormal visceral adiposity, and adipose tissue dysfunction, thus determining a vicious circle." (PMID 33670644, 2021). "Catechins of oolong tea alleviate polycystic ovary syndrome (PCOS) in mice induced by insulin combined with human chorionic gonadotropin." (PMID 34201882, 2021). "For instance, IGFBP-1 being down-regulated by insulin has an important role in the pathophysiology of polycystic ovary syndrome (PCOS) by increasing the free, biological active IGF-I and augmenting the androgen generation in the theca layer." (PMID 35118400, 2021). "We have previously reported significant reductions in VAT and IMAT, as well as maintenance of lean mass, and increased insulin sensitivity during weight maintenance in response to a reduced CHO diet among women with polycystic ovary syndrome (PCOS)." (PMID 32817749, 2020). "Polycystic ovary syndrome (PCOS) as a reproductive disorder disturbs ovarian follicular development, vitamin D stimulated insulin activity, and sex hormone concentrations." (PMID 31673465, 2019). "Thus, it has been suggested that some important differences in polycystic ovaries may facilitate the responsiveness of theca cells to resistin, which may synergise with insulin to increase androgen synthesis." (PMID 31505789, 2019). "Polycystic Ovary Syndrome (PCOS) is a heterogeneous endocrine and metabolic disorder characterized by excessive androgen secretion and abnormal insulin action and affects up to 17% of women worldwide." (PMID 31387252, 2019). "Additionally, high insulin levels in α−/− adult males might be another contributing factor to hyperandrogenemia, as pharmacological doses of insulin are known to stimulate androgen production." (PMID 28357399, 2017). "Intra-abdominal fat mass in polycystic ovary syndrome (PCOS) women shows a positive relation to the up-regulated serum level of fasting insulin, indicating the existence of IR." (PMID 28695131, 2017). "Perturbations in adipokine concentrations have been reported in insulin resistant states such as gestational diabetes mellitus and women with the Polycystic Ovary Syndrome (PCOS)." (PMID 25409499, 2014). "Few studies have tested insulin sensitivity dynamically with an oral glucose tolerance test performed pre- and post-treatment, making it difficult to delineate whether improvements in hyperandrogenemia were a direct effect of metformin or a secondary effect due to decreased insulin concentrations." (PMID 25304843, 2014). "Women with polycystic ovary syndrome (PCOS) are often treated with insulin-sensitizing agents, e.g. thiazolidinediones (TZD), which have been shown to reduce androgen levels and improved ovulatory function." (PMID 18348723, 2008). "Consequently, myo-inositol is regularly utilized in the treatment of polycystic ovary syndrome (PCOS), wherein it acts upon metabolic factors, improving insulin sensitivity and reducing total androgen levels." (PMID 39860564, 2025). "Polycystic Ovary Syndrome (PCOS) is a common endocrine and metabolic disorder characterized by chronic inflammation, insulin resistance, and hormonal imbalances, often leading to infertility and metabolic dysfunction." (PMID 41411269, 2025).
polycystic ovary syndrome (continued). "The patient was on MDI insulin therapy (with prandial insulin lispro and basal insulin glargine) plus metformin (1000 mg twice daily) and an oral contraceptive pill for polycystic ovary syndrome (PCOS)." (PMID 40004833, 2025). "In patients with polycystic ovarian syndrome (PCOS), curcumin reduced FBG (WMD: 3.618; 95%CI: 5.165, −2.071; I2 = 20.4%), and insulin levels (WMD: 1.834; 95%CI: 2.701, −0.968; I2 = 8.4%)." (PMID 40538540, 2025). "Polycystic ovary syndrome (PCOS) is a prevalent endocrinological condition among women of reproductive age, characterized by several well-known symptoms, including hyperandrogenism, anovulation, irregular menstrual cycles, and insulin resistance." (PMID 40943118, 2025). "Environmental toxins, such as bisphenol A, decrease GLUT4 levels, limiting glucose transport into muscle and adipose tissues in response to insulin or exercise, relevant for conditions such as T2DM and polycystic ovary syndrome." (PMID 41440753, 2025). "High insulin levels can inhibit serum SHBG levels, raising the concentration of free bioactive testosterone, ultimately leading to hyperandrogenemia." (PMID 40008316, 2025). "This would further exacerbate the impacts of insulin on ovarian steroidogenesis, hepatic SHBG production and androgen metabolism in peripheral tissues, thereby fueling the hyperandrogenemia-induced arrest of follicle development and oligo/anovulation." (PMID 40013621, 2025). "Polycystic ovary syndrome (PCOS) is a condition characterized by endocrine disorder, anovulation, increasing serum luteinizing hormone (LH) levels and insulin-induced hyperandrogenism." (PMID 40781685, 2025). "It is a condition characterized by a reduced biological response of peripheral tissues to insulin and generally occurs in conjunction with numerous metabolic disorders as well as hormonal disorders such as polycystic ovary syndrome (PCOS) and thyroid dysfunction." (PMID 39339765, 2024). "In addition, it has demonstrated effectiveness in prediabetes and in insulin-resistant conditions, including polycystic ovary syndrome (PCOS)." (PMID 38665260, 2024). "Polycystic ovary syndrome: Polycystic ovary syndrome (PCOS) is a reproductive endocrine disorder that is described by enlarged polycystic ovaries, high levels of androgenic hormones, irregular menstruation, dysregulation of ovulation, and insulin resistance." (PMID 39359934, 2024). "LEP is a regulatory molecule involved in the polycystic ovary syndrome (PCOS) cell model and acts as an upstream regulator of JAK1/STAT3-related inflammation and apoptosis in insulin-treated ovarian granulosa cells (OGCs)." (PMID 38005265, 2023). "The aim of this study was to establish the usefulness of new anthropometric indices and atherogenic indices in the evaluation of metabolic disorders, in particular, glucose and insulin abnormalities in the profiles of women with polycystic ovary syndrome (PCOS)." (PMID 36837921, 2023). "Obesity, polycystic ovaries, acne, hirsutism, elevated FSH: The LH ratio, increased androgens, impaired insulin sensitivity, and prolonged anovulation are all symptoms of polycystic ovarian syndrome." (PMID 38050507, 2023). "There is evidence to suggest that women with polycystic ovary syndrome (PCOS) may experience elevated levels of LH and insulin, which in turn can contribute to increased androgen production." (PMID 37993900, 2023). "The objective of this study was to assess the effect of a 20-week home-based aerobic exercise program on body composition, insulin resistance, and hs-CRP levels in women with polycystic ovarian syndrome." (PMID 35547420, 2022). "It is estimated that in patients with hormonal abnormalities, for example, hypothyreosis or polycystic ovary syndrome (PCOS), the proper insulin response is abolished." (PMID 35684107, 2022).
polycystic ovary syndrome (continued). "Abnormal insulin sensitivity may also accompany other endocrinopathies, such as polycystic ovary syndrome (PCOS), hyperthyroidism, hyperprolactinemia, or hypercortisolemia." (PMID 34836106, 2021). "The nutraceutical may also benefit infertile patients suffering from polycystic ovary syndrome who present distinct changes in the proteome profile of endometrial tissue and abnormal homocysteine metabolism related to oxidative stress, inflammation and insulin resistance." (PMID 32696021, 2020). "Interestingly, all therapeutic approaches used for the correction of insulin homeostasis in obese and MS patients, such as Thiazolidinediones, Metformin, lifestyle modification for weight reduction or bariatric surgery have been proven to produce restoring effects on ovulation and hyperandrogenemia." (PMID 31231310, 2019). "Many approaches aimed at insulin sensitization also reduce lipotoxicity and have been shown to treat PCOS hyperandrogenemia." (PMID 29971102, 2018). "Insulin plays a significant role in the pathogenesis of PCOS, maintenance of hyperandrogenemia, and abnormal placental and foetal steroidogenesis." (PMID 30065244, 2018). "In girls with polycystic ovary syndrome (PCOS), insulin sensitization results in a more favorable endocrine-metabolic outcome than oral contraception; we assessed whether those differences are underscored by changes in circulating fetuin-A." (PMID 30123261, 2018). "Indeed, in the context of PCOS, hyperandrogenemia per se may affect insulin sensitivity." (PMID 25763405, 2014). "In rats with dihydrotestosterone (DHT)-induced polycystic ovary syndrome (PCOS), repeated low-frequency electrical stimulation of acupuncture needles restores whole-body insulin sensitivity measured by euglycemic hyperinsulinemic clamp." (PMID 23349861, 2013). "Furthermore, upregulation of adiponectin receptors, which might reflect an increased need for adiponectin signalling has also been demonstrated in the adipose tissue of women with polycystic ovarian syndrome and in the skeletal muscle of insulin resistant and type 2 diabetic subjects." (PMID 20178558, 2010). "Polycystic ovary syndrome (PCOS) is characterized by a hyperandrogenic state and frequently develops skeletal muscle insulin resistance." (PMID 19169352, 2009). "Women with (n = 24) and without (n = 24) polycystic ovary syndrome were matched for age, insulin sensitivity, TSH, and reasons for thyroid hypofunction." (PMID 40872540, 2025). "Moreover, their insulin sensitivity index was lower, and their triglyceride concentrations and serum AMH concentrations were higher, than the subgroup of women showing hyperandrogenemia only by immunoassays." (PMID 38913250, 2025). "A retrospective study of 113 women with polycystic ovary syndrome assessed metformin’s effects in insulin-resistant and non-insulin-resistant groups." (PMID 40729034, 2025). "In this study, we demonstrated that serum chromogranin A (CgA) levels were significantly elevated in women with polycystic ovary syndrome (PCOS) and showed a positive correlation with body mass index (BMI), insulin, glucose, HOMA-IR, and high-sensitivity C-reactive protein (hs-CRP)." (PMID 41480370, 2025). "Additionally, K2 improved insulin sensitivity in women with polycystic ovary syndrome (PCOS)." (PMID 40718363, 2025). "The decrease in TSH, fasting glucose and glycated hemoglobin, and the improvement in insulin sensitivity were less pronounced in women with than in women without polycystic ovary syndrome." (PMID 40872540, 2025). "In another finding, MO leaves could reduce blood glucose, insulin, and TNF-α levels as well as follicle counts in a polycystic ovary syndrome (PCOS) diabetic mice model." (PMID 37570837, 2023). "Hyperandrogenemia impaired the insulin sensitivity even without weight gain in a pharmacological model of PCOS." (PMID 36768281, 2023).